IL6 (interleukin 6)
Diseases named in the same sentence as IL6 in open-access papers (continued):
Sharing a sentence is not in itself a finding about the gene and the disease.
infection (continued). "The primary microglia cells experienced a 2.1 pg/mL increase in IL-1α, a 9.72 pg/mL increase in IL-1β, a 35.93 pg/mL increase in IL-6, and a 55.09 pg/mL increase in IL-8 signaling at 2hpi during TC-83 infection." (PMID 30101649, 2018). "We found that induction of serum cytokines including IFN-β, CXCL10, and IL-6 following infection of the DNA viruses HSV-1, VACV, and MCMV was severely impaired in Zcchc3−/− in comparison to Zcchc3+/+ mice." (PMID 30135424, 2018). "We found that elevated serum IL-6 was the most prominent among the several inflammatory cytokines we measured upon C. albicans lethal infection in Xiap−/− mice." (PMID 29386580, 2018). "Since an interaction loop of gp91phox-ROS-NF-κB p65 was detected in the senescent macrophages during PAO1 infection, we assessed the production of ROS and the expression of inflammatory cytokines including IL-6, IL-10, and TNFα." (PMID 30050663, 2018). "The addition of anti-IL-6 antibody resulted in significantly lower infection rates in resting cells stimulated by LEC- and LEC+." (PMID 30285810, 2018). "While TNF-α and IL-6 production increased in sole microglia post-infection, CCL2 and IL-1b were upregulated only in μBS." (PMID 30619100, 2018). "Three pro-inflammatory cytokines, namely tumor necrosis factor (TNF), interleukin-1β (IL-1β) and interleukin-6 (IL-6) play a pivotal role in the initial response of the innate immune system to injury or infection." (PMID 30233566, 2018). "Accordingly, in kidney, TNFα, IL6 and IL‐1β mRNA levels were significantly reduced in p38γ/δ−/− and LysM‐p38γ/δ−/− mice at day 1 post‐infection, compared to WT mice." (PMID 29661910, 2018). "Increased IL-6 expression was observed in all of the humanized mouse infection groups except Lo-13-wk, but IL-12 expression in these mice was unimpressive, perhaps due to low T cell engraftment." (PMID 30028878, 2018). "TLR3 deficiency in mice led to increased synthesis of TNF-α, IFN-γ, and IL-10; however, IFN-β, IL-1β, and IL-6 were secreted into the genital tracts of wild-type mice at significantly higher levels than in TLR3-/- mice during early infection." (PMID 29624589, 2018). "IL-1β, TNF-α, or IL-6 present similar patterns of differential expression with a peak at 30 min post-infection when compared with NI cells." (PMID 29942317, 2018). "The authors suggest monitoring serum concentrations of IL-18 and IL-6 for evaluation of disease activity in sJIA and to detect the complication of infection." (PMID 29622022, 2018). "Infection with the hlyU mutant also resulted in decreased secretion of IL-1β and IL-6, the two Th17-polarizing cytokines, although the decreases in the expression of DC surface markers and cytokine mRNAs were not significant." (PMID 30283443, 2018). "Cytokines, especially tumor necrosis factor α (TNF-α), interleukin 1 β (IL-1β), and interleukin 6 (IL-6), are invoked within the immune system in response to surgical stress and infection." (PMID 30405319, 2018). "The levels of IL-2 and TNF-α were significantly increased while the level of IL-6 was obviously decreased in the infection group compared with the normal control group." (PMID 30305831, 2018). "In earlier work, we found that blood-stage infection by the mutant self-resolved at day 12 p.i., displaying an immune signature that comprised elevated IL-6 levels, activation of T and B cells, and antigen-specific IgG2c production." (PMID 28831137, 2017). "The IL-4, IL-6, IL-10, IL-13 levels of Th2 cells continued to increase after infection during the first 9 weeks post-infection and down-regulated thereafter." (PMID 29192177, 2017). "In human VL, there is a strong Th1 cytokine response (IFNγ, IL-1, IL-6, IL-12 and TNFα) at the site of infection, but this is inexplicably unable to control the infection." (PMID 28103263, 2017). "IL-6 is a cytokine involved not only in inflammation and infection responses, but also in the regulation of metabolic, regenerative, and neural processes." (PMID 28714885, 2017).
infection (continued). "The study established cutoffs facilitating diagnosis on day one of infection: IL-6: 31 pg/mL; TNF-α: 17 pg/mL; IL-1β: 1 pg/mL." (PMID 28487810, 2017). "Other studies with phenylpropanoid derivatives, demonstrated a correlation between the downregulation of IL-6 and IL-10 with the control of the infection in the Leishmania-infected macrophages." (PMID 28045892, 2017). "Wild-type infection also induced IL-6, CCL2 (MCP-1), and CXCL1 at day 2 postinfection and suppressed IL-15 production compared to levels in mock-infected animals." (PMID 29138302, 2017). "Within the lungs of infected mice, LANCL2−/− possessed lower levels of IL-10 and higher levels of IL-6 at day 12 post-infection." (PMID 28270815, 2017). "Treatment with Lactobacillus can reduce the incidence of UTIs, and can reduce FBG, homocysteine, and interleukin-6 which play roles in preventing infection for diabetic patients." (PMID 28008148, 2017). "Among those tested the pro-inflammatory mediators IL1α, IL1β, IFNγ and IL-6 and numerous chemokines were substantially elevated in male lungs as early as 21 days post infection." (PMID 28887521, 2017). "The pleotropic cytokine interleukin-6 (IL-6) is involved in a variety of central nervous system (CNS) pathologies including injury, infection, and neurodegeneration." (PMID 28620279, 2017). "Astrocytes are important to brain cells that regulate immunocyte recruitment through the release of cytokines or chemokines, such as IL-1β and IL-6, in response to injuries or pathogen infections." (PMID 28950910, 2017). "At Day 3 post-infection, expression of IL-6, IL-12, GM-CSF, IFN-α, IFN-β, and IFN-γ was also significantly higher in mice not pre-challenged with OVA (PBS/pH1N1) than in mice that were pre-challenged." (PMID 28245238, 2017). "Frozen plasma from 410 children presenting to the Jinja Regional Hospital in Uganda with suspected infection was used to measure biomarkers of endothelial (Angiopoietin-2, sFlt-1, sVCAM-1, sICAM-1) and immune (IL-6, IP-10, sTNFR-1, CHI3L1) activation." (PMID 28419100, 2017). "We have found that the early production of IL-6 after infection promotes the production of the regulatory mediator Interleukin-27 by lung resident immune cells, which in turn drives suppression of otherwise damaging inflammation." (PMID 28953978, 2017). "Our results demonstrate that TFF1 is up-regulated in the acute phase of infection together with IL-1β and IL-6, while is down-regulated in the chronic phase of infection (after 42 days) when IFN-γ, CXCL5, and CXCL15 increase." (PMID 29085807, 2017). "The inflammatory response induced by infection increased IL-10 and IL-6, activating B cells to secrete IgG." (PMID 29312230, 2017). "The resulting data indicate that older children respond with diminished levels of the pro-inflammatory cytokines TNF, IL2 and IL6, as well as Th1-biased chemokines when compared to younger children at the same stage of infection." (PMID 29284469, 2017). "Infection of these cells with viable bacteria induced the strong upregulation of the IL-6 transcript that inversely correlated with gingipain activity." (PMID 28497028, 2017). "Infection of human monocyte derived macrophages with wild-type and esat-6 complemented strain of H37Rv induced strong IL-6 production compared with the cells with esat-6 deletion mutant H37Rv::Δ3875, further supporting the data from mouse macrophages." (PMID 28106119, 2017). "When THP-1 cells were infected with Ms_PE_PGRS41 combined with a stimulatory dose of LPS, TNF-α, IL-6 and IL-1β expression were significantly increased compared to the response to LPS or Ms_PE_PGRS41 infection alone." (PMID 28440335, 2017). "Markers of inflammation including neutrophil infiltration and proinflammatory cytokine production in the BALF, such as TNF-α, IL-1β and IL-6, were determined 8 and 24 hours post-infection." (PMID 28638106, 2017).
infection (continued). "Early after infection, TNFα, IL-1β, IL-6, IL12p70 and IFN-β levels were lower in supernatants from Hdac6-/- cells than in those from Hdac6+/+ cells, and this difference held at 12 and 24 hpi." (PMID 29281743, 2017). "The analysis of the levels of proinflammatory cytokines in geldanamycin-treated mice revealed a significant reduction in TNF-α, IL-6, and IL-1α levels on days 2, 4, or 7 after infection compared with the vehicle-treated and oseltamivir-treated mice." (PMID 28664154, 2017). "IL-6 is critical in enhancing the production of IL-27 by both resident and infiltrating myeloid cells after infection." (PMID 28953978, 2017). "IL-1β and IL-6 both stimulate the proinflammatory response during infection, resulting in severe inflammation, and are known to be upregulated following inoculation with bacteria." (PMID 28970274, 2017). "IL-6 and G-CSF are immune mediators present in the lung during infection and are known to prolong survival of neutrophils in mouse lungs following IAV infection." (PMID 28553293, 2017). "A report from Kaiser's lab found IL-6 was related to symptom scores and temperature values in experimental human infection." (PMID 29285277, 2017). "In Oncorhynchus mykiss larvae, IL-6 was up-regulated after infection with Ichthyophthirius multifiliis and its expression slowly increased until the end of the experiment." (PMID 29182557, 2017). "TNF-α stimulates the production of interleukins that participate in the response to infection or injury, and IL-1β acts on macrophages to release IL-6 and IL-8 related to the pathogenesis of various inflammatory diseases." (PMID 28086859, 2017). "During infection, IL-6 not only plays a major role in induction of an acute phase protein production in the liver but also facilitates expression of many protective genes in the hepatocytes thus stimulating hepatocyte proliferation and their survival." (PMID 28487598, 2017). "HK-Pg infection of BMM induced similar levels of TNFα, IL-12p70, IL-6, IL-10, and IFNβ compared to infection with viable P. gingivalis." (PMID 28824884, 2017). "The extracellular virulence enzyme protease plays a pivotal role in the pathogenesis of S. marcescens during infection and induces interleukin-6 and interleukin-8 mRNA expression through protease-activated receptor 2 (PAR-2)." (PMID 29259923, 2017). "Three days after infection, the IL-6 and TNF-α levels in serum of mice infected by X4550(pYA3334-SspH2-EscI) decreased, while those in mice infected with X4550(pYA3334-SspH2) and X4550(pYA3334) significantly increased (P < 0.05)." (PMID 28468643, 2017). "To gain insight into the systemic response to infection, we measured serum levels of the pro-inflammatory cytokines TNFα and IL-6 on day 5 after infection." (PMID 29190678, 2017). "In this study, white blood cell count, indicating infection, and MOF severity were associated with IL-6 at levels above 8.3 pg/mL." (PMID 28487810, 2017). "The pro-inflammatory cytokines, tumor necrosis factor-α (TNF-α), interleukin-1β (IL-1β) and IL-6, are the first secreted cytokines in a local infection, such as IE." (PMID 29078765, 2017). "As a key mediator of the inflammatory response, IL6 plays a significant role in the inflammatory response to both burn injury and infection." (PMID 28943993, 2017). "Fitting with IL-6’s pleiotropic roles in immunity it is often produced early after infection, but has distinct effects on the outcome depending on the type of infection." (PMID 28953978, 2017). "IL-6 producing by T cells and macrophages drives Th17 cells polarization, stimulates immune response, plays a role in fighting infection." (PMID 29034213, 2017). "In contrast to IFN-β expression, actin polymerization was only partially implicated in DC expression of IL-6 and CXCL1 following infection with the S. suis strain P1/7." (PMID 28894449, 2017).
infection (continued). "In the persistent-infection status, cytokine production was delayed and was composed of a high ratio of proinflammatory versus anti-inflammatory cytokines, such as IL-6, IFN-γ, TNF-α, and IL-10." (PMID 27799331, 2017). "C-reactive protein (CRP) is an acute-phase protein that increases rapidly following interleukin-6 secretion by macrophages and T cells following infection, inflammation and cancer." (PMID 28859644, 2017). "IL-6 is not only involved in inflammation and infection responses, but also in the regulation of regenerative and anti-inflammatory processes, by acting through two signaling modes." (PMID 28188344, 2017). "Animal studies have suggested an intriguing role of IL-6 in the establishment of various infections." (PMID 29078765, 2017). "In these mice, administration of Toll-like receptor (TLR) ligands, including lipopolysaccharides (LPS) and poly(I:C), induces the development of MAS by mimicking an acute infection on a background of high levels of IL-6." (PMID 28095869, 2017). "Anti-HMGB1 pAb-treated septic mice had a survival advantage compared to control mice following secondary infection and treatment was associated with improved antimicrobial responses as mice exhibited increased IL-12 and decreased IL-6 following infection." (PMID 28724977, 2017). "Early depletion of IL-6 significantly reduced the concentration of IL-27 in the airways and lungs throughout infection." (PMID 28953978, 2017). "IL-6 is a pleiotropic acute-phase cytokine involved in the host immune response to infection, reflecting the severity of lower airway inflammation." (PMID 28352642, 2017). "IL-6 is an important inducer of infection defense, crucial for hepatocyte homeostasis, and a potent mitogen of hepatocytes." (PMID 29057809, 2017). "While infected Calu-3 cells secreted more IL-6 into the supernatant than A549 cells 8 h p.i., both cells lines showed a synergistic effect on IL-6 secretion upon super-infection." (PMID 28195157, 2017). "For its part, IL-6 is an important pro-inflammatory cytokine involved in the regulation of host response to tissue injury and infection." (PMID 29075409, 2017). "Here we show that EV-A71 infection transiently increases mouse serum and brain IL-6 levels, which reach peaks on day 2 p.i. and then decline afterward." (PMID 29233145, 2017). "Twenty-four hours post infection, cells were stimulated with LPS and the levels of TNFα and IL-6 were measured." (PMID 28118607, 2017). "In liver tissues, higher levels of IL-1β, IL-6, and IL-8 were induced by treatment with V. vulnificus alone after 3, 6, 12, 24, and 48 hours, but infection in fish treated with TP4 or co-injected with TP4+V." (PMID 28085905, 2017). "At several time points post infection, supernatants were collected and the concentrations of IL-6 and CCL5 determined by BioPlex assay." (PMID 28877226, 2017). "As an acute phase reactant, fibrinogen is up-regulated upon stimulation by inflammatory cytokines, primarily interleukin-6 (IL-6), in response to physiological trauma such as infection/inflammation." (PMID 29099861, 2017). "A greater production of proinflammatory cytokines in hAECs was elicited at later passages together with earlier peaking at 24 hours post infection of IL-6, MIP-1α, and MCP-1 levels." (PMID 28900138, 2017). "IL-6 also represents a keystone cytokine in infection and inflammation, which elicits cellular immune responses to affected cells and mucosal humoral responses directed against reinfection." (PMID 29090023, 2017). "NH1125B, as compared to NH1067B, induced IL-6 earlier during infection and induced greater levels of CCL5 and TNFα transcripts in the MDM of the 2 donors (#67 and #68) presented." (PMID 28877226, 2017). "By comparison, CCL2 and IL-6 were significantly reduced during Opal524R infection at day 2 postinfection." (PMID 29138302, 2017). "Enhanced translation of IL-6 in host cells helps Leishmania to suppress host macrophage activation and promote infection." (PMID 28377760, 2017).
infection (continued). "Previous studies have found that IL-6 limits disease severity after infection by limiting pathogen burden." (PMID 28953978, 2017). "Classical proinflammatory cytokines of early response such as IL-6 or TNF-α were also significantly induced due to infection." (PMID 29348965, 2017). "At the same time, the production of the M1 markers IL12p40, TNF-α and IL-6 during infection, was augmented by knockdown of C/ebpbeta." (PMID 28558034, 2017). "Knockdown of either p38 or ERK1/2 resulted in reduced IL-6 mRNA levels upon super-infection with IV H1N1(M) and S. aureus 6850 compared with control cells." (PMID 28195157, 2017). "Significantly, upregulation of IL-6 was observed in the BMSA vaccinated animal groups 7 to 14 days after infection." (PMID 29312230, 2017). "The observed increase of proinflammatory IL-6 in the lung was also detectable in the blood and reached significant levels in an infection scenario." (PMID 29348965, 2017). "After super-infection, mRNA levels of IL-6, TNFα, CCL3 and CCL5 were substantially increased, especially at 8 h p.i.." (PMID 28195157, 2017). "Examining interleukin (IL)-6 concentrations, endotoxin administration led to an early increase in serum IL-6 levels especially at 2, 4, and 6 h post-infection." (PMID 28836970, 2017). "These cells have the ability to perform phagocytosis, invade tissues, and to produce cytokines such as IL-6 and IL-8 in response to infection." (PMID 28467447, 2017). "Based on the viral growth kinetics, we selected the 48h post infection time point to assess the relative mRNA expression levels of the viral M gene, IL-6 and IFN-β by real-time PCR." (PMID 28114957, 2017). "Interleukin-6 (IL-6) is a cytokine secreted by our body upon infection or trauma to stimulate the immune system response." (PMID 28060820, 2017). "Calcitriol treatment reduced the expression of the pro-inflammatory cytokine IL-6 at the earliest stages of infection, but increased its expression in the later stages of infection." (PMID 28114957, 2017). "Infection induced interleukin-1β, interleukin-6, tumor necrosis factor α, and ectopic trypsin in mouse lungs in a dose- and time-dependent manner." (PMID 27714503, 2017). "aureus super-infection synergistically increases IL-6 levels at both the mRNA and protein levels in different cell lines at several time points of infection." (PMID 28195157, 2017). "IFI16-depleted primary keratinocytes were unable to induce IFN-β or IL-6 mRNA following infection with HSV-1." (PMID 28194029, 2017). "The development of infection activates inflammatory pathways including IL-6 (via NFκβ), but also directly activates hepcidin in AMs and airway epithelial cells via lipopolysaccharide, to cause local iron sequestration." (PMID 28403845, 2017). "In contrast, IL-6 levels in control mice increased to 433.2 pg/mL at 3 days post-infection, similar to the levels after A(H1N1)pdm09 infection." (PMID 28831046, 2017). "The systemic inflammatory response to pathogen infection, local tissue injury or other trauma is mediated by pro-inflammatory cytokines, mainly interleukin 1β (IL-1β), interleukin-6 (IL-6) and tumor necrosis factor (TNF)." (PMID 29185442, 2017). "The close correlation of IL-6 and IL-10 responses has also been observed in rodent infection models and has been proposed to reflect the operation of an immunological homeostatic feedback mechanism in the brain." (PMID 28927234, 2017). "Intranasal infection of adult BALB/c mice with RSV resulted in significantly increased concentrations of IL-6 by 12 hours post infection (p.i.)in the airways (bronchoalveolar lavage (BAL))." (PMID 28953978, 2017). "We detected increased expression of pro-inflammatory KC (protein and mRNA) and Il6 (mRNA) in WT BMMs and to a significantly lesser extent also in MyD88-/- cells at 24 h post infection (p.i.)." (PMID 28445535, 2017). "Mice were treated with one shot of control or anti-IL-6 antibody at the doses of 4.5, 9, or 18 mg/kg on the day of infection." (PMID 29233145, 2017).